SNHG12 (small nucleolar RNA host gene 12)
Diseases named in the same sentence as SNHG12 in open-access papers (continued):
Sharing a sentence is not in itself a finding about the gene and the disease.
tumor (continued). "Small nucleolar RNA host gene 12 (SNHG12), a direct transcriptional target of c-MYC that may promote cell migration by regulating MMP13 expression, has been found to be significantly upregulated in TNBC, its levels correlating with tumor size and presence of lymph node metastasis." (PMID 33572395, 2021). "We established a mouse subcutaneous tumor model by subcutaneous injection of MDA-MB-231 cells, and used exosome-deleted SNHG12 (named as Exo-SNHG12 KD) and corresponding negative control exosome (Exo-SNHG12 KD-MOCK) to treat the mice." (PMID 38833118, 2024).
cancer (65 papers, 2016 to 2025). A tumor composed of atypical neoplastic, often pleomorphic cells that invade other tissues. "Changes in the expression of SNHG12 are associated with tumor cell viability, proliferation, and metastasis and can be used as a prognostic cancer biomarker." (PMID 40353136, 2024). "Among lncRNAs, studies have shown that the small nuclear kernel host gene 12 (SNHG12) is associated with cancer types such as prostate, breast, and gastric cancers." (PMID 40353136, 2024). "Studies have shown that lncRNA SNHG12 is associated with many cancers, such as breast cancer, stomach cancer, osteosarcoma, and glioma, as well as other cancer types." (PMID 36034208, 2022). "RCC1/SNHG3/SNHG12 are not only highly expressed in a variety of cancers, but also are risk factors for poor prognosis." (PMID 36148010, 2022). "Subsequently, it was shown that these cancer-related effects of SNHG12 are underlined by sponging miR-451a." (PMID 35328609, 2022). "Specifically, interactions between SNHG12 and microRNAs have been implicated in several cancer-related cellular processes and signaling pathways." (PMID 35406435, 2022). "The plethora of cancer-related features associated with the disrupted expression of SNHG12 can be a result of the complex network interactions of this lncRNA with miRNAs and proteins." (PMID 35406435, 2022). "The landscape of RCC1/SNHG3/SNHG12 associated with various immune infiltrations in human cancers was demonstrated using TIMER2.0." (PMID 36148010, 2022). "In the analysis RCC1/SNHG3/SNHG12 as a signature for drug-target response difference and association in pan-cancer, Topotecan, TKI258 and Paclitaxal were found which showed significant differences in different expression levels." (PMID 36148010, 2022). "Further research has shown that overexpression of SNHG12 is associated with rapid cancer proliferation, strong invasion and migration, and high rates of metastasis, recurrence, and chemical resistance." (PMID 34372942, 2021). "In this article, we have reviewed SNHG12 emerging functions and clinicopathological association in multiple kinds of cancers and discussed the potential implication in cancer prognosis." (PMID 33124951, 2020). "The potential mechanisms underlying the relationship between aberrant SNHG12 expression and poor clinical prognosis in cancers were well-studied previously." (PMID 33294456, 2020). "The current findings will contribute to the further knowledge of SNHG12 as an effective diagnostic or prognostic biomarker and also provide valuable information for cancer therapy." (PMID 33294456, 2020). "SNHG12 is a small nucleolar RNA host gene (SNHG) implicated in cancer progression." (PMID 38555384, 2024). "Numerous studies have established that SNHG12 is associated with cancers, and could be used as a potential therapeutic target and biomarker for human cancers." (PMID 35721492, 2022). "HuR has emerged as an attractive drug target for cancer therapy, and our works verified that SNHG12 could target HuR, thus regulating many mRNAs associated with cancer progression, which is meaningful and helpful for the development of drugs targeting HuR." (PMID 34195070, 2021). "Additionally, the results of our further subgroup analyses based on cancer types indicated that enhanced expression of SNHG12 was positively associated with better prognosis in ESCC." (PMID 33294456, 2020). "Moreover, the violin plot implicated that SNHG12 expression level was significantly correlated with pathological stage in human pan-cancers." (PMID 33124951, 2020). "Besides, it should be noted that certain previous study employed serum samples to detect endogenous SNHG12 expression levels with relatively good diagnostic efficiency in specific cancer." (PMID 33294456, 2020). "We have highlighted the target molecules of SNHG12, which may serve as potential diagnostic and prognostic biomarkers, and/or as targets for novel strategies for cancer therapy." (PMID 31620362, 2019).
cancer (continued). "Therefore, SNHG12 overexpression was closely associated with poor survival in cancer patients." (PMID 33124951, 2020). "We drew a conclusion based on the meta-analysis outcome (HR = 1.94, 95% CI: 1.56–2.41, P < .001) that solid malignant tumor patients with high lncRNA SNHG12 expression is associated with poor survival rate, indicating that lncRNA SNHG12 may be an unfavorable prognosis factor to cancer." (PMID 33031264, 2020). "Therefore, elevated SNHG12 expression was associated with poor survival and unfavorable clinical outcomes in various cancers, and therefore might be a potential prognostic biomarker in human cancers." (PMID 33124951, 2020). "High expression of RCC1/SNHG3/SNHG12 in patients with a variety of cancers including ACC, KIRP, LAML, LGG, LIHC, and PRAD predicted lower overall survival and disease free survival." (PMID 36148010, 2022). "SNHG12 was originally discovered in cancer cells and plays a key role in the proliferation and migration of cancer cells." (PMID 36275741, 2022). "One such lncRNA, small nucleolar RNA host gene 12 (SNHG12), is ectopically expressed in a variety of malignancies and protects cancer cells against immune attack by crosstalk with the polarization of effector immune cells, including macrophages and T cells." (PMID 35658874, 2022). "The expression of SNHG3 and SNHG12 in pan-cancer showed high similarity with the expression of RCC1." (PMID 36148010, 2022). "Overall, RCC1/SNHG3/SNHG12 can be used as a marker of poor prognosis in the early stages of pan-cancer." (PMID 36148010, 2022). "High expression of RCC1/SNHG3/SNHG12 was poor in early DFS in pan-cancer and correlated with low DFS in ACC, LGG, LIHC, and PRAD." (PMID 36148010, 2022). "Meanwhile, combined with the results of survival analysis, the role of RCC1/SNHG3/SNHG12 in some cancers is dominated by suppression of immune response." (PMID 36148010, 2022). "Small nucleolar RNA host gene 12 (SNHG12) produces a long RNA that is overexpressed in cancer cells." (PMID 35524329, 2022). "Using StarBase v2.0 software (screening conditions: pan-cancer number: 5, medium, clip data), several miRNAs were predicted to have a high probability of binding to SNHG12." (PMID 34239888, 2021). "This study aimed to evaluate the value of SNHG12 as a biomarker in the prognosis and clinical characteristics of various cancer patients." (PMID 34372942, 2021). "Previous literature has outlined the role of SNHG12 in the tumorigenesis of several cancers, but its significance in GC requires further elucidation." (PMID 33994849, 2021). "Next, the data were extracted from studies examining SNHG12 expression, overall survival and clinicopathological features in patients with malignant tumors." (PMID 34372942, 2021). "SNHG12 is a long noncoding RNA (lncRNA) commonly involved many types of cancers in the contexts of tumorigenesis, migration and drug resistance." (PMID 34195070, 2021). "Elevated expression of SNHG12 has been identified to correlate with proliferation, invasion and metastasis of human cancer cells, thereby modulating the survival of cancer patients." (PMID 33787057, 2021). "At present, increasing evidence has shown that the abnormally high expression of SNHG12 plays a carcinogenic role in various malignant tumors." (PMID 34372942, 2021). "Our study confirmed that the high expression level of SNHG12 is closely related to the clinicopathological characteristics and prognosis of patients and is a new predictive biomarker for various cancer patients." (PMID 34372942, 2021). "Long non-coding RNA (lncRNA) small nucleolar RNA host gene 12 (SNHG12) plays important roles in the pathogenesis and progression of cancers." (PMID 33994849, 2021).
cancer (continued). "Cancer patients with higher SNHG12 expression had unfavorable overall survival (OS), recurrence-free survival (RFS), and disease-free survival (DFS)." (PMID 33124951, 2020). "First, to confirm the regulatory pattern of SNHG12 in ESCC, we found that SNHG1, SNHG7, and SNHG12 were three upregulated lncRNAs in ESCC tissues through Cancer RNA‐Seq Nexus analysis." (PMID 32239639, 2020). "Online cross-validation in TCGA dataset further indicated that cancer patients with upregulated SNHG12 expression had worse overall survival and disease-free survival." (PMID 33124951, 2020). "Members of SNHG family, including SNHG12, are supported to promote cancer development via regulating Wnt/β‐catenin pathway." (PMID 32239639, 2020). "Even though many studies have indicated the prognostic significance of SNHG12 in human cancers, the further mechanisms remain indistinct." (PMID 33124951, 2020). "Accumulating studies revealed that SNHG12 served as a ceRNA, similar to miRNA “sponge,” to modulate multiple cancer-related pathophysiological processes." (PMID 33294456, 2020). "Taken together, these mechanisms indicated that SNHG12 acted as important regulators in the progress of cancers and further supported our findings that increased SNHG12 expression predicted poor OS in cancer patients." (PMID 33294456, 2020). "Small nucleolar RNA host gene 12 (SNHG12) is a newly identified lncRNA with aberrant expression in various human cancers." (PMID 33124951, 2020). "We confirmed that SNHG12 expression was upregulated in CD133+ ESCC cells compared with CD133‐ cancer cells, and we also validated that SNHG12 was mainly distributed in cytoplasm." (PMID 32239639, 2020). "Considering that SNHG12 has complex function mechanisms in cancers, more studies are still needed to thoroughly explore the association of SNHG12 in different types of cancer." (PMID 33124951, 2020). "According to previous fundamental studies, SNHG12 had a series of ways to affect the tumorigenesis and development of these cancers." (PMID 33294456, 2020). "Anyway, this result indicated that the function of SNHG12 would be different in diverse cancer types as a result of different interaction mechanisms and participating partners." (PMID 33294456, 2020). "According to qRT‐PCR data, SNHG12 expression was obviously upregulated in CD133+ ESCC cells compared with the CD133‐ cancer cell group." (PMID 32239639, 2020). "The result demonstrated that overexpression of SNHG12 also predicted poor DFS in cancers (HR = 1.40; 95% CI: 1.12-1.76; P = 0.004)." (PMID 33294456, 2020). "Upregulated expression of SNHG12 showed significant association with unfavorable survival and indicated worse clinicopathological outcomes in multiple kinds of human cancer, and therefore might serve as a promising prognosis biomarker and therapeutic target for cancers." (PMID 33124951, 2020). "Recently, increasing studies suggested that lncRNA SNHG12 was aberrantly expressed in kinds of cancers." (PMID 33124951, 2020). "For LSCC prognostic lncRNAs, H19, MALAT1, NEAT1, CYTOR and SNHG12 were ranked as the first five of this directly-related-to-cancer list." (PMID 32024523, 2020). "To comprehensively analyze the pathways regulated by SNHG12 in GC cells, we conducted a cancer pathway microarray analysis in MGC-803 cells." (PMID 31808752, 2019). "SNHG12 was dramatically upregulated in unpaired and paired cancer tissues compared with para-cancerous tissues, both in GC and in other malignancies." (PMID 31808752, 2019). "In this review, we discuss the proposed mechanistic roles of SNHG12 in the pathogenesis of several human cancers, including the regulatory molecules of SNHG12 in modulating several hallmarks of cancer." (PMID 31620362, 2019). "Our cancer pathway microarray and bioinformatic analyses suggested that SNHG12 regulates the PI3K/AKT pathway." (PMID 31808752, 2019).
cancer (continued). "Taken together, cancer pathway microarray and bioinformatics analyses, RNA pulldown assays, Western blotting and immunohistochemistry revealed that SNHG12 induces GC tumorigenesis by activating the phosphatidylinositol 3-kinase/AKT pathway." (PMID 31808752, 2019). "Cumulative evidences demonstrated the aberrant overexpression of Small Nucleolar RNA Host Gene 12 (SNHG12) in diverse human cancer." (PMID 31114448, 2019). "In line with the in vivo results from cancer patients, SNHG12 mRNAs were up-regulated in all of subject cancer cell lines than in 293T cells and renal epithelial HK-2 cells." (PMID 31114448, 2019). "Small nucleolar RNA host gene 12 (SNHG12) is one of many long non-coding RNAs involved in the progression of several types of cancer." (PMID 31293373, 2019). "Small nucleolar RNA host gene 12 (SNHG12), as one of the long non-coding RNAs (lncRNAs), plays an oncogenic role in various cancers, however, its role in the chemoresistance of non-small cell lung cancer (NSCLC) is unclear." (PMID 29137407, 2017). "SNHG12 is a member of small nucleolar RNA host genes (SNHGs), which have been indicated to contribute to cancer progression." (PMID 28793054, 2017). "The lncRNA small nucleolar RNA host gene 12 (SNHG12) is overexpressed in a variety of cancers." (PMID 35847935, 2022). "Recent studies have shown that SNHG3 and SNHG12 are dysregulated in a variety of cancers." (PMID 36148010, 2022). "While DNA methylation changes explain the aberrant expression of SNHG12 in cancer cells, emerging data indicate that SNHG12 may control the expression of neighboring genes probably by changing epigenetic marks on histones and affecting their transcription." (PMID 35406435, 2022). "The lncRNA SNHG12 is upregulated and inhibits tumor inhibition of miRNAs in many cancer types." (PMID 36034208, 2022). "Patients with high RCC1/SNHG3/SNHG12 expression in pan-cancer have poor early OS." (PMID 36148010, 2022). "SNHG12 exerts a carcinogenic effect in a variety of cancers." (PMID 35597996, 2022). "The diversity of interactions with microRNAs showcased the complex molecular network influenced by SNHG12 and indicated that it might serve as a new therapeutic target in human cancers." (PMID 35406435, 2022). "The pan-cancer correlations between RCC1/SNHG3/SNHG12 and immune checkpoints were displayed." (PMID 36148010, 2022). "Here, we wanted to observe whether the role of SNHG12 in tumors is the same, that is, to suppress or promote cancer." (PMID 34372942, 2021). "The lncRNA small nucleolar RNA host gene 12 (SNHG12) is overexpressed in various cancer types." (PMID 34944877, 2021). "Although previous studies reported that SNHG12 or YWHAZ could bind to HuR in other cancer types, this study is the first report that SNHG12 regulates the stability of YWHAZ by binding to HuR." (PMID 34195070, 2021). "Taken together, our present study suggested a novel ceRNA network, in which SNHG12 could promote the malignancy of ccRCC although competitively binding with miR‐30a‐3p and consequently release the expression of its downstream cancer‐related genes." (PMID 33787057, 2021). "It has been acknowledged that SNHG12 is dysregulated in many cancers." (PMID 33787057, 2021). "Recent published studies have shown that upregulated SNHG12 could drive the tumorigenesis and cancer phenotypes such as proliferation, metastasis, invasion, and anti-apoptosis." (PMID 33124951, 2020). "Similarly, SNHG12 also had cross-talk with other cancer-related pathways including PI3K/Akt pathway and Wnt/β-catenin pathway." (PMID 33124951, 2020). "Increasing evidence shows that SNHG12 promotes the proliferation and metastasis of cancer cells." (PMID 32927431, 2020). "Collectively, SNHG12 has shown its tumorigenesis functions and clinical significance, and may serve as a prognosis biomarker for various human cancers." (PMID 33124951, 2020). "Taken together, SNHG12 has the potential serving as a prognostic biomarker in pan-cancer patients." (PMID 33124951, 2020).